KCNIP3 (potassium voltage-gated channel interacting protein 3)
Description:
Calcium-dependent transcriptional repressor that binds to the DRE element of genes including PDYN and FOS. Affinity for DNA is reduced upon binding to calcium and enhanced by binding to magnesium. Seems to be involved in nociception (By similarity). Regulatory subunit of Kv4/D (Shal)-type voltage-gated rapidly inactivating A-type potassium channels, such as KCND2/Kv4.2 and KCND3/Kv4.3. Modulates channel expression at the cell membrane, gating characteristics, inactivation kinetics and rate of recovery from inactivation in a calcium-dependent and isoform-specific manner. May play a role in the regulation of PSEN2 proteolytic processing and apoptosis. Together with PSEN2 involved in modulation of amyloid-beta formation.
Synonyms: DREAM; KChIP3; CSEN
Tractability: Small molecule: it has a binding pocket of medium quality. Antibody: UniProt places it where antibodies can reach, with high confidence; its Gene Ontology location is reachable by antibodies, with high confidence. PROTAC: UniProt records ubiquitination sites on it.
Gene: Protein-coding gene on chromosome 2 (95,297,327 to 95,386,081, forward strand). Ensembl gene ENSG00000115041.
Subcellular location: Cytoplasm; Cell membrane; Endoplasmic reticulum; Golgi apparatus; Nucleus
Subcellular location (Human Protein Atlas): Vesicles
Pathways (Reactome):
Gene expression (Transcription): Regulation of NPAS4 gene transcription
Muscle contraction: Phase 1 - inactivation of fast Na+ channels
Gene Ontology:
Molecular function: DNA-binding transcription repressor activity, RNA polymerase II-specific; protein binding; RNA polymerase II cis-regulatory region sequence-specific DNA binding; calcium ion binding; potassium channel regulator activity; calcium-dependent protein binding; core promoter sequence-specific DNA binding; DNA binding; magnesium ion binding
Biological process: negative regulation of transcription by RNA polymerase II; protein localization to plasma membrane; regulation of potassium ion transmembrane transport; regulation of signal transduction; signal transduction; response to magnesium ion
Cellular component: cytoplasm; endoplasmic reticulum; Golgi apparatus; nucleus; plasma membrane; cytosol; voltage-gated potassium channel complex; protein-DNA complex
Genetic constraint (gnomAD): Loss-of-function variants: 28 observed, 30.73 expected, observed/expected ratio (o/e) 0.91, 90% interval 0.67 to 1.25. The upper end of that interval is the gene's LOEUF score, 1.25, which puts it in group 5 of 6, group 1 being the genes least tolerant of losing a copy. Missense variants: 285 observed, 339.42 expected, observed/expected ratio (o/e) 0.84, 90% interval 0.76 to 0.93. Synonymous variants: 130 observed, 135.09 expected, observed/expected ratio (o/e) 0.96, 90% interval 0.83 to 1.11.
Homologues: Orthologues: chimpanzee KCNIP3 (99% identical), pig KCNIP3 (94% identical), macaque KCNIP3 (93% identical), guinea pig KCNIP3 (92% identical), tropical clawed frog kcnip3 (83% identical), rat Kcnip3 (80% identical), rabbit KCNIP3 (78% identical), zebrafish kcnip3b (76% identical), mouse Kcnip3 (75% identical), dog KCNIP3 (63% identical), Drosophila melanogaster CG5890 (40% identical), Caenorhabditis elegans ncs-7 (31% identical), and 2 more. Paralogues in human: KCNIP2 (62% identical), KCNIP4 (62% identical), KCNIP1 (55% identical), NCS1 (33% identical), HPCAL1 (30% identical), HPCA (30% identical), NCALD (30% identical), VSNL1 (29% identical), HPCAL4 (28% identical), RCVRN (25% identical), GUCA1B (23% identical), CLXN (21% identical), and 2 more.
Diseases named in the same sentence as KCNIP3 in open-access papers:
KCNIP3 is named in the same sentence as 86 diseases in open-access papers, as found by Europe PMC text mining. Sharing a sentence is not in itself a finding about the gene and the disease. The quoted sentences say what the papers report.
breast carcinoma (11 papers, 2020 to 2026). "However, MRPL13 and KCNIP3 were predicted to be risk factors associated with poor prognostic outcome in breast cancer." (PMID 32977823, 2020). "For KCNIP3, it has been identified as a potential biomarker for the early detection of basal-like breast cancer." (PMID 32977823, 2020). "In alignment with our results, we speculated that MRPL13 and KCNIP3 may be served as poor prognostic biomarkers, and their downregulation may have a better prognosis of breast cancer." (PMID 32977823, 2020). "In conclusion, ABCA3, CCL22, FOXJ1, MAP2K6, and IL1RN may serve as good prognostic factors, while KCNIP3 and MRPL13 may be poor prognostic biomarkers to predict the recurrence and prognosis of breast cancer." (PMID 32977823, 2020). "ABCA3, CCL22, FOXJ1, IL1RN, and MAP2K6 may serve as good prognostic factors, while KCNIP3 and MRPL13 may be poor prognostic factors for the prognosis of breast cancer." (PMID 32977823, 2020).
Alzheimer disease (8 papers, 2014 to 2025). A progressive, neurodegenerative disease characterized by loss of function and death of nerve cells in several areas of the brain leading to loss of cognitive function such as memory and language. "In line with the role of KCNIP3 for cellular function, diseases associated with KCNIP3 gene mutations include Alzheimer’s disease." (PMID 32182846, 2020). "The first was located in the potassium channel-encoding gene Kcnip3 in chromosome 2, a gene involved in neuronal excitability that was previously associated with Alzheimer’s disease." (PMID 24887417, 2014). "GSK3B may play a role in neuroinflammation, neuronal apoptosis, and accumulation of phosphorylated tau in AD, while KCNIP3 may play a functional role in the neurobiology of Alzheimer's disease by being part of these gene interaction networks commonly associated with neurodegenerative processes." (PMID 40537925, 2025).
glioblastoma (8 papers, 2013 to 2025). The most malignant astrocytic tumor (WHO grade IV). "While considering glioblastoma, we found SOX2, DUSP6, SLC24A3, KCNIP3, and DPP4 to be differentially the most upregulated, which have previously been found to be effective in glioblastoma formation and prognosis." (PMID 38769480, 2024).
depression (4 papers, 2017 to 2025). "Importantly, Kcnip3-/- rats displayed stronger aversion to the pain-associated compartment, higher anxiety level and aggravated depression-like behavior." (PMID 30740043, 2019). "As negative emotions might aggravate the pain responses, the higher anxiety and depression level in Kcnip3-/- rats might contribute to the increased sensitivity to pain." (PMID 30740043, 2019). "Therefore, decreased dopaminergic and serotonergic neurotransmission might contribute to the enhanced pain-induced aversion, anxiety- and depression-like behaviors in Kcnip3-/- rats under both basal and inflammatory pain conditions." (PMID 30740043, 2019). "Notably, Kcnip3-/- rats displayed stronger aversion to the pain-paired compartment in the CPA test and showed higher levels of anxiety and depression post CFA injection." (PMID 30740043, 2019). "In addition to increased anxiety-like behavior, Kcnip3-/- rats showed stronger aversion mood in the CPA test and showed more depression-like behavior in the forced swimming test and sucrose preference test both under basal and inflammatory pain conditions." (PMID 30740043, 2019).
glioma (4 papers, 2021 to 2025). A benign or malignant brain and spinal cord tumor that arises from glial cells (astrocytes, oligodendrocytes, ependymal cells). "We used this score to screen and verify the biological effects of KCNIP3 in gliomas, both in vitro and in vivo." (PMID 41445790, 2025). "Functionally, we demonstrated that KCNIP3 overexpression in U87 and LN229 glioma cells significantly inhibited cell proliferation, invasion, and migration." (PMID 41445790, 2025).
Anxiety (3 papers, 2019 to 2025). Intense feelings of nervousness, tension, or panic often arise in response to interpersonal stresses. "Our previous studies indicated that Kcnip3-/- rats displayed high basal anxiety levels in the elevated plus maze test." (PMID 30740043, 2019). "Combined with our previous results showing the higher basal anxiety level of Kcnip3-/- rats, the potential anxiolytic action of KChIP3 protein was supposed." (PMID 30740043, 2019). "Altogether, these results suggest that Kcnip3 knockout exacerbates inflammatory pain-induced anxiety-like behavior in rats." (PMID 30740043, 2019). "Herein, we examined the anxiety level of Kcnip3-/- rats during inflammatory pain." (PMID 30740043, 2019). "However, both our studies from elevated plus maze and open field tests indicated that Kcnip3-/- rats had a higher anxiety level compared to the wild-type rats post CFA injection." (PMID 30740043, 2019). "Another study in female Kcnip3-/- mice also showed that the Kcnip3 gene deletion did not affect the anxiety level in the ovariectomized mice receiving or not receiving estradiol injections." (PMID 30740043, 2019).
cervical cancer (2 papers, 2020 to 2021). A primary or metastatic malignant neoplasm involving the cervix. "The disruption of repressive p130-DREAM (KCNIP3) complexes by human papillomavirus 16 E6/E7 oncoproteins has been found to be essential for cell cycle progression in cervical cancer cells." (PMID 32391054, 2020).
diabetic retinopathy (2 papers, 2015 to 2021). "Alternative splicing of Kcnip3, a gene associated with diabetic retinopathy, is assumed to contribute to the diverse functions of the KCNIP proteins in the cells." (PMID 33880624, 2021). "rs201189528 spatially connects with several other loci: SUGP1 (19p13.11), which affects serum lipid levels and dyslipidemia; LPP (3q28), which is associated with T2D in American Indians; and KCNIP3 (2q21.1), which is associated with diabetic retinopathy." (PMID 26191039, 2015).
Dyskinesia (2 papers, 2018 to 2019). A movement disorder which consists of effects including diminished voluntary movements and the presence of involuntary movements. "In addition, L-DOPA-induced dyskinesia was decreased in daDREAM mice, while genetic deletion of Kcnip3 potentiated the intensity of dyskinesia." (PMID 30740043, 2019).
papillary thyroid carcinoma (2 papers, 2018 to 2025). "Silencing of KCNIP3 enhances the epithelial–mesenchymal transition and proliferation via activating the Wnt/β-catenin pathway in papillary thyroid carcinoma." (PMID 40709170, 2025).
Cognitive impairment (1 paper, 2020). Abnormal cognition is characterized by deficits in thinking, reasoning, or remembering. "Kcnip3 mRNA was downregulated in AGAT-/- mice, which revealed severe cognitive impairment." (PMID 32182846, 2020).
metastatic melanoma (1 paper, 2017). A melanoma that has spread from its primary site to another anatomic site. "Genes encoding high-mobility group protein A1 (HMGA1), Kv Channel Interacting Protein 3 (KCNIP3) and Apolipoprotein B (APOB) shared promoter hypomethylation in all metastatic melanoma cell lines." (PMID 28030832, 2017).
tumor (43 papers, 2007 to 2026). "Collectively, these results suggest that KCNIP3 suppresses tumor cell proliferation and invasion both in vitro and in vivo." (PMID 41445790, 2025). "ATP1B1, GPC3, KCNIP3, and PRLR transcript levels in tumor tissues were significantly lower in PTCs than in NT, whereas LCN2, LGALS1 and SCD1 expression was upregulated in PTC compared with NT." (PMID 27249794, 2016). "Multiple stepwise linear regression identified SSTR2, TIMP1 and KCNIP3 as predictors of the response to the acute SA test and SA treatment and RORC as a predictor of tumor size." (PMID 23825587, 2013).
KCNIP3 also shares sentences with these, for which no sentence is quoted: cancer (43 papers); neuroblastoma (9); Huntington disease (7); ovarian carcinoma (7); gastrointestinal stromal tumor (4); meningioma (4); cognitive decline (3); colon carcinoma (3); colorectal cancer (3); epilepsy (3); Fanconi anemia (3); head and neck cancer (3); lung carcinoma (3); neurodegenerative disease (3); retinoblastoma (3); Stroke (3); amyotrophic lateral sclerosis (2); bone marrow failure syndrome (2); embryonal carcinoma (2); infection (2); lung adenocarcinoma (2); lung fibrosis (2); microcephaly (2); neurological diseases (2); osteosarcoma (2); prostate carcinoma (2); systemic sclerosis (2); ameloblastoma (1); amyloidosis (1); anaplastic thyroid carcinomas (1).
A further 43 diseases each share a sentence with KCNIP3 in 1 paper.